EGFR (epidermal growth factor receptor)
Diseases named in the same sentence as EGFR in open-access papers (continued):
Sharing a sentence is not in itself a finding about the gene and the disease.
tumor (continued). "Besides that, the tumor cell lines SCC25 and Detroit 562 represent genetic changes encountered in EGFR/RAS/RAF/MEK/ERK and EGFR/PI3K/AKT/mTOR signaling that play a pivotal role in cancer development and resistance." (PMID 33718274, 2021). "The heterodimers formed between EGFR and HER2 may circumvent the anti-tumor effects of HER2-targeted therapies." (PMID 33986665, 2021). "Drug inhibition of EGFR signaling may thus release a feedback constraint on FGFR2b which manifests off-target as IL1-mediated skin toxicity, predicting on-target tumor response." (PMID 34007277, 2021). "Post-mortem analysis of one GBM with a mosaic pattern of RTK amplifications showed that tumor cells with PDGFRA amplifications were limited to the bulk of the tumor, while EGFR amplifications were observed in the cell population present at areas of infiltration." (PMID 33673104, 2021). "Patient selection for anti-EGFR therapy was further improved by taking into account the sidedness of the primary tumour, since patients with right-sided primary tumours do not benefit from the addition of anti-EGFR to chemotherapy." (PMID 34253874, 2021). "The GPER/EGFR/ERK axis is further responsible for blocking cell cycle progression, promoting apoptosis, and inhibiting cell growth in HCC cells, finally leading to reduced tumor viability both in vitro and in vivo." (PMID 33767999, 2021). "FAM188B knockdown induced EGFR downregulation and inactivation of survival-related signaling molecules, indicating that FAM188B could be a potential target to control tumor metastasis." (PMID 33440835, 2021). "Systemic vectorization of this drug in EGFR-targeted bacterial minicells showed significant tumor reduction and immune activation with no side effects in immunocompetent breast and colorectal murine models but also lung and colorectal human cancer xenografts." (PMID 33761944, 2021). "After treatment with 5 mg/kg/day SH-1028, a moderate tumor growth inhibition was observed in A431 (wild-type EGFR) tumor xenografts, suggesting that SH-1028 and its metabolites are not entirely inactive against tumor cells with wild-type EGFR." (PMID 33986687, 2021). "They found that EGFR-negative tumor cells that were not sensitive to EGFR/CD3 BiTE were efficiently lysed when co-cultured with EGFR-positive tumor cells." (PMID 34832954, 2021). "Therefore, a promising approach is represented by small carrier proteins able to interact specifically and with a high affinity (in the picomolar to the nanomolar range) with several targets overexpressed in tumor cells such as HER2, EGFR, and IGF-1R." (PMID 34439990, 2021). "EGFR is an established activator of the HIF pathway, contributing to tumour progression." (PMID 34298636, 2021). "c-MET and EGFR regulate the synthesis and secretion of several angiogenic growth factors, including basic fibroblast growth factor (bFGF), vascular endothelial growth factor (VEGF), and interleukin (IL)-8, in tumor cells." (PMID 34512327, 2021). "From a therapeutic point of view, our results strongly support the use of bispecific antibodies as a dual targeting strategy, both neutralizing EGFR on tumor cells and recruiting FcγRIIIa+ TAN in contact with tumor cells to boost the ADCC-mediated tumor cell lysis." (PMID 34211852, 2021). "In addition to effects on EGFR signaling, the ability to mediate ADCC is an important contributor to cetuximab anti-tumor activity." (PMID 34831127, 2021). "Another mutant-selective EGFR allosteric inhibitor, JBJ-04-125-02, blocks the EGFRL858R/T790M/C797S signaling both in vitro and in vivo and has antitumor activity against an NSCLC xenograft tumor." (PMID 34207383, 2021).
tumor (continued). "Compared with micelles without peptide modification, FALGEA modification showed higher recognition ability to EGFR-positive tumor cells, while the reverse sequence of FALGEA did not have such specificity." (PMID 34277592, 2021). "Xenograft cancer studies using rag2Δ/Δ, il2rga−/− zebrafish allow facile, single-cell imaging of T cell–mediated tumor killing by CAR T cell, BiTE, and APEC immunotherapies and identified EGFR-targeted immunotherapies as an effective treatment for rhabdomyosarcoma muscle cancers." (PMID 34415995, 2021). "Of note, the level of EGFR expressed by epithelial cells was not statistically significantly different compared to that expressed by tumor cells (p = 0.51), suggesting additional factors to be involved in modulating NK cell cytolytic activity." (PMID 34771609, 2021). "It is reported that the EGFR/PI3K/Akt/mTOR signaling pathway and inhibition of STAT3 may be the imperative mechanisms mediating oxymatrine-regulated anti-tumor action of GBM cells." (PMID 33768139, 2021). "In vitro studies using RAS-WT mCRC tumor cells have emphasized that an anti-VEGF mAb may activate the RAS pathway, promoting resistance to anti-EGFR antibodies." (PMID 34768686, 2021). "Although it is known that EGFR-mediated NF-κB activation is involved in tumor development, the signaling axis is not well elucidated." (PMID 34769306, 2021). "EGFR non-shedders have a smaller baseline tumor target lesion size, the fewest detectable genomic alterations and the lowest VAFs of these mutations." (PMID 34638411, 2021). "EGFR mutant NSCLC now reflects an amended view of oncogene addiction, one that can be escaped following the selective pressure applied by EGFR inhibitors due to heterogeneity within the tumor as well as epigenetic and genetic adaptations." (PMID 34944063, 2021). "By tagging anti-EGFR mAb (cetuximab) to the surface of liposomes, we not only achieve TNBC tumor targeting but also could integrate the immunotherapy of the mAb." (PMID 34359650, 2021). "Similarly, CDK4/6i can resensitize therapy-resistant tumors to EGFR inhibitors, MET/TRK inhibitors, and MEK inhibitors by suppressing the growth of tumor cells in multiple pre-clinical models, in vitro and in vivo." (PMID 33809714, 2021). "The same study unveiled that 67% of the responsive patients were not correctly identified as such, which corresponds to a 33% recall due to their NSCLC tumours not being EGFR-mutant." (PMID 34680436, 2021). "To evaluate whether FGFR1 upregulation occurs in clinical NSCLC tumors that progressed on EGFR-TKI treatment, we examined the FGFR1 mRNA expression in paired tumor samples from EGFR-mutant NSCLC patients at baseline and after progression to EGFR-TKI treatment." (PMID 34267282, 2021). "EGFR-targeted cetuximab or nimotuzumab antibody dependent cellular cytotoxicity (ADCC) and activated NK cells were both shown to induce natural killer (NK)-DC crosstalk, which resulted in DC maturation and EGFR-specific CD8(+) T-cell priming and enhanced anti-tumor effects." (PMID 35048023, 2021). "After disease progression on first‐line EGFR‐TKI, disease flare may occur when TKI is abruptly discontinued, including aggravation of symptoms, an increase in tumor size, and increased FDG uptake on PET‐CT." (PMID 34374490, 2021). "KRAS testing is important in patients with mCRC as KRAS-mt tumours do not respond to anti-EGFR adjuvant therapy." (PMID 34940086, 2021). "We further evaluated the differences in the tumor-infiltrating immune cells (TICs) in the immune microenvironment between groups with different levels of SPP1 expression, and those with or without EGFR mutation." (PMID 34178613, 2021).
tumor (continued). "Moreover, intravenously injected Ze affibody was predominantly distributed on EGFR-expressing cells, thus accumulating in LS174T tumor grafts in mice." (PMID 33754061, 2021). "The dimerization of EGFR can activate important pathways such as the ERK pathway, thereby activating a variety of transcription factors and inducing the proliferation and differentiation of tumor cells." (PMID 33931584, 2021). "Since FoxP3 is predominantly expressed in Tregs, our data implied that there was no substantial increase of Treg populations within EGFR overexpressing tumours relative to wt EGFR tumours." (PMID 35052732, 2021). "Once the role of miR-375 was demonstrated in the CTGF-EGFR pathway, we verified whether CTGF or EGFR activation could reverse the tumour-suppressive changes induced by miR-375." (PMID 33407703, 2021). "It has been reported that EGFR-TKIs are cytostatic rather than cytotoxic agents, which do not eradicate micrometastatic tumor cells even after a marked clinical response." (PMID 34067376, 2021). "Crosstalk between EGFR and other members of the HER family or unrelated RTKs, as mediated by coexpression of RTKs in the same tumor, neutralize the growth-inhibitory properties of EGFR-targeted therapies due to redundancy in mechanisms of PI3K-AKT and RAS-ERK activation." (PMID 32646879, 2021). "Both EGFR and PKC-δ signaling interplay with NF-κB-mediated tumor progression." (PMID 34765548, 2021). "Therefore, exploration of novel mechanisms for EGFR-mediated immune escape and tumor promotion and reversal of the suppressive TME is essential to improve the efficacy of ICIs in NSCLC patients with EGFR activation." (PMID 33537094, 2021). "Formation of EGFR homodimers or heterodimers (i.e., with HER2) trigger intracellular pathways that lead to cancer cell proliferation, apoptotic arrest, activation of invasion and metastasis, and stimulation of tumour-induced neovascularisation." (PMID 34771633, 2021). "EGFR signaling includes ERK and AKT pathways, which are often found increased in tumor cells." (PMID 34298835, 2021). "Moreover, the GO analysis revealed that most of the angiogenic growth factors and their receptors involved in tumor progression, including VEGF, EGF, EGFR, and FGF, were differentially expressed." (PMID 33803224, 2021). "We then analyzed the tumor volumes on the left (A549) and right (A549-CXCL13) sides and found that EGFR-CXCR5-CAR-T was more effective in eradicating A549-CXCL13 (right-side tumor) than classical EGFR-CAR-T." (PMID 34553036, 2021). "Collectively, these results advance our understanding of ST6Gal-I’s tumor-promoting function by highlighting a role for ST6Gal-I in EMT, which may be mediated, at least in part, by α2-6-sialylated EGFR." (PMID 33148698, 2021). "Moreover, CMTM7 is capable of increasing the internalization of EGFR, and further suppresses activation of the AKT signaling pathway during tumor pathogenesis." (PMID 34294040, 2021). "In addition, the increasing use of circulating tumor DNA in blood to clarify resistance mechanisms may favor the reporting of amplification of mutated EGFR, because the inevitable contamination by nonmalignant cells hinders clinicians from accurately analyzing the copy numbers of wild‐type genes." (PMID 33471376, 2021). "Since combined blockade of ILT4 and PD-L1 showed a synergistic effect on tumor inhibition in vitro, we explored whether combination therapy could increase ICI treatment potential in EGFR wild-type NSCLC in vivo." (PMID 33537094, 2021). "In human samples (NSCLC tumour tissues and adjacent tissues from NSCLC patients (stages I-IIIa)), there was an inverse correlation between curcumin administration and the activity of the EGFR/AKT/NF-κB pathway." (PMID 34834295, 2021). "EGFR mutants found in tumor patients are not internalized or transported to the MVBs/lysosomes, resulting in enhanced and prolonged activation of EGFR and its downstream MAPK signaling that is essential for tumor cell proliferation and invasion." (PMID 33996800, 2021).
tumor (continued). "Immunohistochemically, the tumor was positive for immunohistochemical markers for CK AE1/AE3, Vimentin, S100, Brachyury, epithelial membrane antigen (EMA) and epidermal growth factor receptor (EGFR)." (PMID 34717660, 2021). "As an intracellular tyrosine kinase domain necessary for signaling pathways, EGFR overexpression is detected in most NSCLC cells and its regulation could be essential to manage tumor progression." (PMID 34209829, 2021). "Tumor samples showed a downregulation of miR-7-5p and conversely an upregulation of IRS2 and EGFR." (PMID 34381564, 2021). "As was seen in RD RMS xenografted cells, EGFR CAR T cells efficiently infiltrated into the tumor and effectively killed RMS tumor cells over time in three additional xenograft models irrespective of disease subtype (n = 5 zebrafish/arm; P < 0.006, Student’s t test)." (PMID 34415995, 2021). "It is particularly important to study the differences in tumor microenvironment (TME) between patients with and without EGFR mutation." (PMID 34178613, 2021). "The expression of EGFR and PLK1 mRNA was compared in normal and tumor tissues of LUAD patients." (PMID 34503223, 2021). "While the EGFR-specific Fab blocks EGF signaling, the PD-L1-specific Fab can inhibit immune checkpoints and, in combination, both could facilitate an enhanced tumor selectivity." (PMID 34040611, 2021). "One study demonstrated that EGFR‐targeted BiTEs produced by CAR‐T cells could induce effective and specific anti‐tumor activity against heterogeneous tumors and mitigate against the effects of EGFRvIII which causes antigen loss." (PMID 34431224, 2021). "Given that RTK coactivation plays an important role in tumor response to RTK-targeted therapy, we sought to use molecular imaging to understand and visualize the interplay between MET, EGFR, and HER2 receptor dynamics in our PDX model, which expresses all 3 receptors." (PMID 32646879, 2021). "KRAS mutations have been associated with lack of response for EGFR TKIs and due to the paucity of KRAS targeted therapies in the past, KRAS mutant tumor have been hard to treat with targeted therapies." (PMID 34257540, 2021). "EGFR is highly expressed by ERMS tumors and cell lines, in some cases contributing to tumor growth." (PMID 34359977, 2021). "Furthermore, some oncogenic genes like EGFR, CDK6, YAP1, and MMP7 were amplified in the TP53INP2-low patients while some tumor suppressor genes including CDKN2A, KLF6, and PTEN were deleted." (PMID 33897760, 2021). "An overexpression of cellular adhesion protein, vascular cell adhesion molecule-1 (VCAM-1) in human GBM cells resulted from an activation of epidermal growth factor receptor (EGFR), was found to augment communication between macrophages and tumor cells, thus promoting tumor invasion." (PMID 34439380, 2021). "We found that EGFR mutations were more common in patients with ADC, irrespective of sex, age, or tumor stage." (PMID 33407425, 2021). "To determine whether the anti-proliferative activity of anti-EGFR/VEGFR2 BsAb observed in cellular models can translate to similar activity in vivo, we evaluated the anti-tumor activity in athymic nude mice bearing MDA-MB-231 xenografts." (PMID 33804477, 2021). "Moreover, the EGFR wild-type LADC subject with LncRNA H19 SNP rs217727 or rs2107425 was correlated to severe tumor grade, especially higher tumor T status." (PMID 33799753, 2021).
tumor (continued). "Moreover, effective anti-tumor responses were observed when the Notch inhibitor GSI (DBZ) and the EGFR inhibitor (Erlotinib) were used under low doses of individual inhibitors as compared to the doses normally used for the testing." (PMID 33473104, 2021). "Immunohistochemistry (IHC) report was strongly positive for PD-L1 in 95% of the tumor cells, negative ALK gene rearrangement, and no EGFR mutation was detected." (PMID 33070259, 2021). "The blockade of the cross talk between EGFR and IFR1R signaling by EGa1-AG538-L may also alleviates the tumor resistance when EGa1 or AG358 is used alone." (PMID 33464410, 2021). "EGFR and VEGF inhibitors are the key therapy in many tumor types." (PMID 33562829, 2021). "However, our strategy could be more effective in the induction of tumor regression, as it causes direct cell damage rather than solely targeting EGFR kinase activity, and should work in resistant tumors that retain membrane EGFR." (PMID 35052426, 2021). "These hub biomolecules of tumor stroma network, AR, GATA2, miR-124, TOR1AIP1, ESR1, EGFR, STAT1, miR-192, GATA3, COL1A1, may give crucial information about tumorigenesis." (PMID 33907495, 2021). "Cerebral magnesium was significantly higher in patients with MGMT methylation and no EGFR amplification in tumor and contralateral side (p < 0.0001)." (PMID 34298788, 2021). "Furthermore, patients with mCRC with tumour budding and/or KRAS-mt respond poorly to anti-EGFR therapy." (PMID 34940086, 2021). "Concordance between EGFR CNV assessed by ddPCR and FISH on tumour tissue was 98%." (PMID 33199443, 2021). "It was reported that EGFL7 binds to EGFR wildtype but not to the active mutant EGFR variant III, leading to b-catenin activation and upregulation of EGFL7 expression and tumor growth." (PMID 33804387, 2021). "Secondly, not all of the patients had the re-biopsy tumor tissue at resistant point of the third-generation EGFR TKIs." (PMID 33842353, 2021). "Meanwhile, Kaplan–Meier analysis showed that high expression of LRRK2 correlates to a better prognosis; knockdown of LRRK2 expression attenuated the proliferation ability of ccRCC tumor cell lines; protein–protein interaction network analysis showed that LRRK2 interacts with HIF1A and EGFR." (PMID 34217264, 2021). "Therefore, PIK3CA can affect tumor proliferation, invasion, apoptosis, and angiopoiesis in KIRC by regulating MAPK1 and EGFR." (PMID 34367282, 2021). "Our results delineate a mechanism of PD-L1 degradation and cancer escape from immunity via EGFR-GSK3α-ARIH1 signaling and suggest GSK3α and ARIH1 might be potential drug targets to boost anti-tumor immunity and enhance immunotherapies." (PMID 33879767, 2021). "It has been found that EGFR protein can be transferred from tumour cells to non-cancerous cells via exosomes which leading to downregulation of the VEGF pathway." (PMID 35127511, 2021). "Hence, sustained EGFR activation is achieved through multiple molecular mechanisms and contributes to EMT-related intra- and inter-tumor heterogeneity in HNSCC." (PMID 34771518, 2021). "EGFR is a membrane-bound receptor tyrosine kinase protein that activates downstream intracellular signaling pathways, including MAPK (RAS/RAF/MEK/ERK), PI3K/AKT, and JAK/STAT3 signaling, and plays a role in tumor cell growth, proliferation and differentiation." (PMID 34925375, 2021). "Furthermore, qRT-PCR analysis revealed that SLC2A3, FOXO3, EGFR and GPC1 were upregulated in tumor samples." (PMID 33962639, 2021). "Further trials are warranted to elucidate the role of anti-PD-1/PD-L1 agents in the treatment paradigm for patients with EGFR-mutant NSCLC and determine whether baseline tumour PD-L1 expression is predictive of improved durability of response." (PMID 33012782, 2021).